CLDN24 (claudin 24)
Description:
Plays a major role in tight junction-specific obliteration of the intercellular space, through calcium-independent cell-adhesion activity.
Synonyms: CLDN21
Tractability: Antibody: UniProt places it where antibodies can reach, with medium confidence; UniProt predicts a signal peptide or a membrane-spanning region; its Gene Ontology location is reachable by antibodies, with medium confidence. PROTAC: its protein half-life has been measured.
Gene: Protein-coding gene on chromosome 4 (183,321,764 to 183,322,426, reverse strand). Ensembl gene ENSG00000185758.
Subcellular location: Cell junction, tight junction; Cell membrane
Gene Ontology:
Molecular function: structural molecule activity
Cellular component: bicellular tight junction; plasma membrane; membrane
Genetic constraint (gnomAD): Loss-of-function variants: 1 observed, 0.91 expected, observed/expected ratio (o/e) 1.1, 90% interval 0.28 to 1.9. That is too few expected variants to judge how well the gene tolerates losing a copy. Missense variants: 217 observed, 248.69 expected, observed/expected ratio (o/e) 0.87, 90% interval 0.78 to 0.98. Synonymous variants: 103 observed, 102.33 expected, observed/expected ratio (o/e) 1.01, 90% interval 0.86 to 1.19.
Homologues: Orthologues: chimpanzee CLDN24 (96% identical), macaque CLDN24 (95% identical), dog CLDN24 (78% identical). Paralogues in human: CLDN22 (87% identical), CLDN25 (49% identical), CLDN6 (35% identical), CLDN5 (33% identical), CLDN1 (33% identical), CLDN9 (33% identical), CLDN19 (32% identical), CLDN4 (32% identical), CLDN3 (31% identical), CLDN7 (31% identical), CLDN14 (31% identical), CLDN17 (30% identical), and 10 more.
Diseases named in the same sentence as CLDN24 in open-access papers:
CLDN24 is named in the same sentence as 4 diseases in open-access papers, as found by Europe PMC text mining. Sharing a sentence is not in itself a finding about the gene and the disease. The quoted sentences say what the papers report.
tumor (2 papers, 2015 to 2019). "Significant genetic losses were assumed to contain potential tumour-suppressor genes: DPYD (1p21.3); CLDN22, CLDN24, ING2, CASP3, SORBS2 (4q34.2-q35.1); DEFB (8p23.1)." (PMID 26019623, 2015).
CLDN24 also shares sentences with these, for which no sentence is quoted: bacterial infection (1 paper); cancer (1); influenza (1).